GFAP (glial fibrillary acidic protein)
Diseases named in the same sentence as GFAP in open-access papers (continued):
Sharing a sentence is not in itself a finding about the gene and the disease.
infection (continued). "PBS controls exhibited baseline staining for ICAM-1, as well as classical staining patterns for IBA1+ professional phagocytes and GFAP, a marker expressed exclusively in astrocytes in the CNS; mice at day 2 of infection had no overt pathological changes." (PMID 28742087, 2017). "Immunofluorescence analysis showed that BMPR-IB infection increased the expression of GFAP protein, which is a recognized marker of astrocytic differentiation, whereas BMPR-IB knock-down decreased the expression of GFAP protein." (PMID 22650359, 2012). "On the other hand, infection did not alter the content of GFAP, the morphology of GFAP-positive astrocytes, nor did it alter the distribution of GFAP-positive astrocytes in the brains of rats treated with either water or GTA." (PMID 23134838, 2012). "Reactive astrocytes produce a variety of factors in response to injury and infection, so we examined whether astrocytes expressed MMP-7 during EAE by co-immunostaining for glial fibrillary acidic protein (GFAP)." (PMID 19267908, 2009). "The absence of sustained elevations in circulating NfL and GFAP nearly two years after infection suggests that ongoing symptoms may involve mechanisms beyond overt neuronal or astrocytic injury." (PMID 41892619, 2026). "We observed limited coexpression of mCherry and GFP following infection with either construct, indicating that NFI factors may be required for appropriate glial-specific expression of the GFAP minipromoter construct, as suggested by previous findings in astrocytes." (PMID 40388211, 2025). "To assess whether infection had an effect on OL viability and glial activation, we performed immunostaining on brain slices from mice at day 8 p.i. using antibodies specific for OLs (SOX10+), mature OLs (SOX10+APC+), microglia (Iba1+) and astrocytes (GFAP+)." (PMID 37596606, 2023). "However, during chronic O. felineus infection in experimental animals, only the number of GFAP+ cells (not FSP+ fibroblasts) significantly increased during the course of infection, remaining, nevertheless, comparatively small." (PMID 36355906, 2022). "Moreover, at 3.5 days following infection, GFAP-Math5-Brn3b-GFP AAVs did not drive GFP expression in either Sox9-immunoreactive astrocytes or RGCs immunoreactive for Rbpms and Brn3a." (PMID 34671605, 2021). "However, GFAP labeling is homogeneous and therefore does not distinguish whether infection induces one population of reactive astrocytes or if subpopulations with distinct functional roles emerge." (PMID 40635167, 2025). "Indeed, a caveat that plagues the field is the heterogeneity of astrocytes which should not be defined by GFAP expression only and as the data are based on GFAP + it is a far reach to conclude the lack of infection of all astrocytes as no other markers were used." (PMID 36639783, 2023). "To define the localization of the virus within the eye and determine whether the infection leads to changes to ocular morphology, we stained eye sections with antibodies specific to the virus (antibody clone EVU-302), neurons (anti-neurofilament 160), and glial cells (GFAP) at 15, 30, and 60 dpi." (PMID 29802245, 2018). "GFAP levels were elevated significantly with infection in CD46+ mice, but not in CD46+/IFNγ-KO mice, in comparison to uninfected controls at 7 dpi, suggesting that localized reactive astrogliosis may be occurring in the hippocampus in the presence of IFNγ during infection." (PMID 27178303, 2016). "The two patients in this study developed the condition following infection, and tests for NMDAR, CASPR2, LGI1, AMPA, GABA, DPPX, mGluR, GAD65, MOG, GFAP, and AQP4 antibodies were all negative." (PMID 38765268, 2024). "Very limited regions of GFAP positive cells co-stained with IE/E, indicating astrocytes were not preferentially infected with CMV by 14 days post infection." (PMID 38504123, 2024).
infection (continued). "We observed widespread infection in astrocytes regardless of the SARS-CoV-2 strain, with approximately 50% of infected cells expressing glial fibrillary acidic protein (GFAP)." (PMID 38741604, 2024). "Minimal or no overlap was observed between viral RNA and GFAP or CD68, indicating minimal or no infection in the astrocytes and microglia, respectively." (PMID 35533188, 2022). "Immunofluorescence staining was used to co-label SOCS3 and GFAP proteins and it was found that SOCS3 was highly expressed in astrocytes but not in other cells after infection." (PMID 35296090, 2022). "At day 7, the GFAP signal was weak, and neurons were almost absent in infected untreated cells, whereas infected hf-NPCs treated with heparin prior to infection differentiated into neurons (TUJI-positive cells) and astrocytes (GFAP-positive cells) unlike untreated cells." (PMID 36121298, 2022). "However, we can essentially rule out this possibility because following infection by GFAP-GFP AAVs, there were no GFP+ cells present in the GCL that co-localized with either Pax2, Sox9, GFAP, or S100β which are astrocyte markers." (PMID 34671605, 2021). "Immunofluorescence (IF) for GFAP, a classical marker for radial glia (RG) and astrocytes in the developing cortex, revealed a pronounced difference in the ZIKV infected frontal cortex compared to the control (or day 7 or 14 post-infection fetuses without vertical transfer of virus)." (PMID 30657788, 2019).
neurodegenerative disease (201 papers, 2009 to 2026). A disorder of the central nervous system characterized by gradual and progressive loss of neural tissue and neurologic function. "Only with such a thorough and meticulous approach can we move beyond superficial associations and harness GFAP as a precise, reliable biomarker for astrocyte reactiveness in neurodegenerative diseases." (PMID 40346659, 2025). "Because both NfL and GFAP were similarly associated with the risk of any neurodegenerative disease, we then evaluated the associations of NfL and GFAP with the risk of each neurodegenerative disease by conducting separate, diagnosis-specific analyses." (PMID 41206819, 2025). "NfL was broadly associated with the risk of several neurodegenerative diseases, while GFAP was more selectively associated with AD." (PMID 41206819, 2025). "In this study, we highlight associations between the widely studied neurodegenerative disease biomarkers, NfL, t-tau, GFAP and YKL-40, across three biological fluids in HTT gene-positive patients." (PMID 39849121, 2025). "Further validation is required to assess GFAP’s consistency across different blood-based diagnostic assays to improve its clinical applicability in AD and other neurodegenerative diseases." (PMID 40690136, 2025). "The gene encodes a protein that is a major intermediate filament of astrocytes, and the GFAP has been linked to many neurodegenerative diseases as a potential biomarker." (PMID 40137462, 2025). "This altered ratio of GFAP isoforms is the root cause for GFAP aggregation, a tell-tale sign that happens universally in the neurodegenerative diseases such as AxD and AD." (PMID 41002922, 2025). "We used Cox proportional hazards models to evaluate the association of NfL and GFAP with incident neurodegenerative disease." (PMID 41206819, 2025). "The present study demonstrates a strong relation between IRAP and the microtubule variant MAP2, and furthermore, the neurodegenerative disease marker GFAP is also altered by IRAP inhibition." (PMID 39596085, 2024). "By offering insights into GFAP’s role in reactive astrogliosis, we demonstrate its clinical relevance in enhancing diagnostic accuracy and advancing our understanding of neurodegenerative diseases." (PMID 39554381, 2024). "Most worryingly, are serum GFAP levels an indicator of neuroinflammatory and/or neurodegenerative diseases, or are serum GFAP levels associated with drug-induced (SSRIs) cellular toxicity ?" (PMID 40980097, 2023). "Surprisingly, E. cava decreased the activity of markers associated with inflammation (NF-kB and STAT3) and a neurodegenerative disease marker (glial fibrillary acidic protein, beta-amyloid) in the cerebrum and hippocampus of mice." (PMID 37111229, 2023). "Astrocytes respond to brain injury via hypertrophy and the upregulation of GFAP, a hallmark of reactive gliosis in various neurodegenerative diseases." (PMID 37569457, 2023). "We also stained spinal cord sections with an antibody for the glial fibrillary acidic protein (GFAP), a marker expressed by astrocytes that is up-regulated in association with inflammatory processes in neurodegenerative diseases." (PMID 37958767, 2023). "Glial fibrillary acidic protein (GFAP), comprises the cytoskeleton of astrocytes within the central nervous system, and is implicated in neurodegenerative diseases." (PMID 38292036, 2023). "GFAP in CSF is associated with cognitive performance and is increased in different neurodegenerative diseases compared to controls and in CU individuals with AD pathology compared to those without." (PMID 36192766, 2022). "Activation of astrocytes with an increased expression of GFAP and S100β is a hallmark of brain diseases, including common late-onset neurodegenerative diseases, ischemic brain injuries, and epilepsy." (PMID 33441619, 2021). "Reactive astrocytes are another hallmark of neurodegenerative diseases and can be assessed by astrocyte marker glial fibrillary acidic protein (GFAP) staining." (PMID 32107387, 2020).
neurodegenerative disease (continued). "Finally, we explored the relationship between NfL and GFAP levels in the pre-diagnostic phase of neurodegenerative diseases." (PMID 41206819, 2025). "However, despite growing interest in their pre-diagnostic value, direct comparative studies of NfL and GFAP across neurodegenerative diseases remain scarce, making their temporal trajectories and disorder-specific predictive potential not fully understood." (PMID 41206819, 2025). "Elevated NfL and GFAP levels could potentially serve as indicators of disrupted sleep and sleep‐related disorders in individuals at risk for neurodegenerative diseases." (PMID 38421124, 2024). "This is in direct contrast to reports of unique cell populations associated with the development of neurodegenerative diseases such as Alzheimer’s70 and Huntington’s71, including the appearance of multiple populations of reactive astrocytes characterized by GFAP upregulation." (PMID 38890340, 2024). "In LBD biofluid studies, GFAP levels in blood and CSF are higher than controls, similar to AD, variably different from other neurodegenerative diseases, and may be associated with cognitive performance." (PMID 37569491, 2023). "The association between cognition and blood‐derived GFAP levels may be smaller in the context of normal aging and increase more saliently among those with an underlying neurodegenerative disease process." (PMID 36056631, 2022). "This reduction of GFAP-ir astrocyte fibers may be an important mechanism underlying the excitotoxicity of neurons in neurodegenerative diseases." (PMID 31798416, 2019). "Finally, it should also be noted that other neurodegenerative diseases are associated with reactive astrogliosis and the consequent up-regulation of GFAP gene activity." (PMID 21985529, 2011). "Some authors report that cytoskeleton proteins, such as vimentin and GFAP, are involved in several cellular functions and in stress conditions, so their expression is considered a biomarker of astrocyte activation and astrogliosis caused by lesions or neurodegenerative diseases." (PMID 39459191, 2024). "We validate the performance of this system by detecting the glial fibrillary acidic protein, a biomarker for traumatic brain injury and neurodegenerative diseases, in plasma samples and demonstrate high femtomolar-level sensitivity (∼40 pg/mL)." (PMID 41873753, 2026). "Increased levels of serum glial fibrillary acidic protein (sGFAP), an astrocytic intermediate filament, were found in various neuroinflammatory and neurodegenerative diseases." (PMID 40518460, 2025). "GFAP positivity increase has been well described in neurodegenerative diseases, such as Alzheimer's, in which astrocytes have been postulated as possible therapeutic targets." (PMID 39962362, 2025). "Nfl and GFAP levels are elevated in various neurodegenerative diseases, including AD, to similar extents." (PMID 40901664, 2025). "IU1 treatment in mouse embryonic fibroblasts (MEFs) and HEK293 cells promoted degradation of several proteasome substrates associated with neurodegenerative diseases, such as tau, TDP‐43, ATXN3, and glial fibrillary acidic protein (GFAP)." (PMID 39840724, 2025). "Structurally, pigs possess gyrencephalic brains that resemble the human brain in cortical organization, gray-to-white matter ratios and the expression of biomarkers such as GFAP/clusterin, which are relevant to neurodegenerative diseases." (PMID 40483385, 2025). "There were only a few reports where GFAP acetylation was related to the disease pathogenesis of neurodegenerative diseases." (PMID 41002922, 2025). "Elevated GFAP levels have, therefore, been found in the CSF of patients with various neurodegenerative diseases compared to controls." (PMID 39289040, 2025). "Sometimes, phosphorylation of GFAP can be detrimental and can trigger deleterious consequences in some neurodegenerative diseases." (PMID 41002922, 2025).
neurodegenerative disease (continued). "Astroglial proteins, such as GFAP, have already been shown to be candidate markers for neurodegenerative diseases." (PMID 39297507, 2024). "Increased levels of GFAP in cerebral spinal fluid and plasma can be seen in patients with traumatic brain injuries and neuroinflammatory and neurodegenerative diseases." (PMID 39596085, 2024). "GFAP levels were measured in 396 serum or plasma samples, comprising both healthy controls and patients with neurodegenerative diseases." (PMID 39594187, 2024). "In pathological conditions, such as traumatic brain injury (TBI), neurodegenerative diseases, and inflammatory disorders, astrocytes become activated and increase their GFAP expression." (PMID 39594187, 2024). "Pl-GFAP levels are indeed markedly increased in AD compared to healthy controls or other neurodegenerative diseases (e.g., FTD)." (PMID 38791145, 2024). "Growing evidence supports the clinical utility of blood GFAP levels as a biomarker for neuroinflammatory and neurodegenerative diseases, as well as CNS involvement in systemic conditions." (PMID 39766495, 2024). "In clinical validation studies, GFAP levels were significantly elevated in patients with neurodegenerative diseases compared to healthy controls." (PMID 39594187, 2024). "Elevation in the GFAP protein level is a distinguished feature of degenerative diseases such as MS and NMOSD." (PMID 39064479, 2024). "In neurodegenerative disease states, astrocytes respond to environmental cues by upregulating the expression of glial fibrillary acidic protein (GFAP)." (PMID 37035740, 2023). "Several studies have reported a correlation between GFAP and cognitive performance in PD and other neurodegenerative diseases." (PMID 37932720, 2023). "GFAP is an astrocytic intermediate filament which signals astrocytic damage or activation, the presence of which is found in neurodegenerative diseases and neuroinflammatory conditions." (PMID 37545721, 2023). "Glial scar occurring in neurodegenerative diseases is formed by the interaction between astrocytes and fibrous tissue around the central damage core and is partly triggered by GFAP elevation." (PMID 37886003, 2023). "As Müller cells upregulate GFAP in response to injury and in neurodegenerative diseases, GFAP serves as a sensitive marker for retinal stress and damage." (PMID 37298126, 2023). "Some neuromarkers for infectious (Distemper Virus, Herpesvirus type 1), neoplasic (GFAP), and neurodegenerative diseases (neurofibrillary tangles, β -amyloid, α-synuclein, ubiquitin, and laforin) have also been tested." (PMID 35202291, 2022). "Growing research supports the fundamental role of reactive astrocytosis in neurodegenerative disease with elevated glial fibrillary acidic protein (GFAP) expression as a primary marker." (PMID 36056631, 2022). "Growing evidence suggests the potential clinical application value of blood GFAP levels in numerous neuroinflammatory and neurodegenerative diseases, as they can be used to detect even subtle injury to the CNS." (PMID 36263422, 2022). "Inflammation markers such as the glial fibrillary acidic protein (GFAP) can be used to measure the intensity of inflammation after brain injury or during distinct stages of neurodegenerative diseases." (PMID 36233034, 2022). "Additional evaluation of the association between GFAP and GrimAge is necessary to better understand the potential role of GFAP in shortened time-to-death and the implications for altering the course of neurodegenerative diseases." (PMID 36153327, 2022). "In general, GFAP is recognized as a biomarker for many internal and external stimuli, as well as neurodegenerative diseases in the CNS." (PMID 34445296, 2021). "Increased levels of astrogliosis marker glial fibrillary acidic protein (GFAP) in CSF and plasma, have been described in different neurodegenerative diseases." (PMID 34893073, 2021).